BRAF (B-Raf proto-oncogene, serine/threonine kinase)
Diseases named in the same sentence as BRAF in open-access papers (continued):
Sharing a sentence is not in itself a finding about the gene and the disease.
metastatic melanoma (continued). "In short, dual inhibition of BRAF and MEK to unresectable or metastatic melanoma with BRAF V600 mutation is superior to inhibiting BRAF or MEK separately in the form of ORR, PFS, OS, and quality of life." (PMID 36254250, 2022). "For example, in 2013, dabrafenib was approved as a B-Raf proto-oncogene (BRAF) inhibitor for treating BRAF-V600K-mutant metastatic melanoma." (PMID 36233210, 2022). "BRAF and MEK inhibitors target therapies (TT) and AntiPD1 immunotherapies (IT) are available first-line treatments for BRAF v600 mutant metastatic melanoma patients." (PMID 36046043, 2022). "The combination of trametinib and dabrafenib, a BRAF inhibitor, was approved for the treatment of BRAF-V600E/K-mutant metastatic melanoma in 2014." (PMID 35646101, 2022). "While BRAF/MEK inhibitors or immune checkpoint inhibitors (ICI) have revolutionized the treatment of patients with metastatic melanoma, approximately 50% of patients still experience fatal outcomes." (PMID 35159045, 2022). "BRAF inhibitors (such as Vemurafenib and Dabrafenib) have been approved for the treatment of metastatic melanoma, since they significantly improve progression-free and overall survival, although resistance is rapidly acquired." (PMID 35805902, 2022). "A phase III trial (BREAK3) compared dabrafenib with dacarbazine in BRAF V600 E patients with unresectable or metastatic melanoma." (PMID 35406444, 2022). "Concurrent administration of BRAFi and MEKi is now an established therapeutic protocol for the treatment of BRAF V600E-mutant metastatic melanoma and an adjuvant treatment in routine clinical practice." (PMID 35174094, 2022). "Three combinations of BRAF and MEK inhibitors have been approved by the US FDA for metastatic melanoma with BRAF V600E or V600K mutations: cobimetinib plus vemurafenib, dabrafenib plus trametinib, and encorafenib plus binimetinib." (PMID 36254250, 2022). "Although 70% of patients with metastatic melanoma respond upon treatment with a combination of BRAF and MEK inhibitors, acquired resistance is frequent, especially in those with high tumoral burden at baseline." (PMID 35159045, 2022). "Vemurafenib is a strong and highly selective BRAF V600 inhibitor which was approved by the FDA for the treatment of unresectable or metastatic melanoma." (PMID 36358795, 2022). "Specifically, these researchers looked at spartalizumab (an anti-PD-1 antibody), in combination with dabrafenib and trametinib, versus placebo plus dabrafenib and trametinib in patients with BRAF V600-mutant unresectable or metastatic melanoma." (PMID 35954441, 2022). "For this reason, many of the targeted therapies used in the treatment of metastatic melanoma include BRAF inhibitors such as dabrafenib, vemurafenib, encorafenib, and MEK1/2 inhibitors such as binimetinib." (PMID 35311078, 2022). "A phase III trial, comparing treatment with BRAF inhibitors versus combined treatment with BRAF and MEK inhibitors in patients with BRAF-mutated metastatic melanoma, did indeed find that pain was a major HRQL issue in this population." (PMID 36116420, 2022). "The BRAF inhibitor vemurafenib, approved for treating patients with BRAF V600E-mutant and unresectable or metastatic melanomas, rapidly induces cutaneous adverse events, including hyperkeratotic skin lesions and cutaneous squamous cell carcinomas (cSCC)." (PMID 35174094, 2022). "Metastatic melanoma is one of the most aggressive tumors, with frequent mutations affecting components of the MAPK pathway, mainly protein kinase BRAF." (PMID 36613518, 2022). "Our real-world data indicate that sequential treatment with front-line CPI is associated with favorable tumor control and overall survival in a subgroup of previously untreated BRAF-mutant metastatic melanoma patients." (PMID 35565212, 2022). "BRAF inhibitors now constitute the main therapeutic approach for the treatment of metastatic melanoma." (PMID 36358912, 2022).
metastatic melanoma (continued). "The advent of immune-checkpoint inhibitors (CPI) and BRAF/MEK-directed targeted therapy (TT) has improved the treatment landscape of patients with BRAFV600-mutant metastatic melanoma." (PMID 35565212, 2022). "IMspire150 is the first phase 3 study evaluating a triplet combination that led to regulatory approval for the treatment of BRAF V600E/K mutant metastatic melanoma." (PMID 36505793, 2022). "As a MEK inhibitor, trametinib has been approved for the treatment of BRAF-V600E metastatic melanoma." (PMID 36233210, 2022). "To date, no routine biomarkers have been approved to determine early response in patients with metastatic melanoma treated with BRAF-MEK inhibitors." (PMID 35203494, 2022). "Overall, primary resistance occurs in 40 to 65% of metastatic melanoma cases either treated with targeted therapies, i.e., BRAF/MEK inhibitors or ICI, highlighting the need for new therapeutic options." (PMID 35159045, 2022). "Both immune checkpoint inhibitors (ICI) and molecularly targeted therapy with BRAF and MEK inhibitors (BRAF/MEKi) are standard options for patients with BRAFV600-mutated, unresectable, or metastatic melanoma." (PMID 35682684, 2022). "BRAF inhibition was also associated with an increase in T-cell exhaustion markers TIM-3 and PD1 in tumors of patients with metastatic melanoma." (PMID 36505793, 2022). "It has been approved by the FDA in combination for the treatment of metastatic melanoma with BRAF inhibitors." (PMID 35677427, 2022). "This study has demonstrated that targeting adenosine pathway combined with BRAF inhibition enhanced immune responses to metastatic melanoma." (PMID 36131912, 2022). "Vemurafenib is a well-known BRAF inhibitor that the FDA has authorised for treating metastatic melanoma with BRAF V600E." (PMID 36428683, 2022). "In clinical studies, the phase I trial BRAF in melanoma 1 (BRIM-1) showed a complete or partial tumor regression in 81% of patients with BRAF-V600E mutant metastatic melanoma." (PMID 36358912, 2022). "In particular, n = 6 independent samples of BRAF wild type metastatic melanoma were compared to a reference array representing a pool of healthy tissues enriched with non-dysplastic melanocytes (biological average of n = 4 independent samples)." (PMID 35805902, 2022). "The approval of three BRAF/MEK inhibitor combinations with different toxicity profiles offers multiple treatment options for patients with BRAF-mutant metastatic melanoma." (PMID 33804800, 2021). "Despite the remarkable success of BRAF inhibitors and immunotherapy in patients with metastatic melanoma, only a subset of patients benefits from these therapies." (PMID 33915880, 2021). "Combined BRAF and MEK targeted therapies (TT) are current standard regimen for BRAF mutated metastatic melanoma (MM)." (PMID 34207200, 2021). "In BRAF-mutant metastatic melanoma, BRAF and MEK inhibitors have proven to improve survival, although half of the patients develop resistance within a year." (PMID 33925915, 2021). "The introduction of new systemic treatment modalities, including immunotherapy and BRAF inhibitors, has significantly improved the prognosis of patients with metastatic melanoma." (PMID 33915880, 2021). "Targeted therapy including BRAF and MEK inhibitors and immune checkpoint inhibitors are the standard of care for unresectable locally advanced and metastatic melanomas with BRAFV600E/K mutations." (PMID 34831002, 2021). "Apparently, in metastatic melanoma cell line A375M, treatment with vemurafenib inhibits BRAF, thereby stopping signal transduction to the ERK protein, and it reactivates this signaling pathway after acquiring resistance to vemurafenib." (PMID 34680379, 2021). "We retrospectively recruited 331 metastatic melanoma patients treated with CII as first line: 162 NRAS-mutant/BRAF wild-type and 169 wt/wt." (PMID 33530579, 2021).
metastatic melanoma (continued). "In patients with BRAF‐mutant metastatic melanoma, targeted therapy using BRAF and MEK inhibitors can lead to significant tumor regression." (PMID 32767816, 2021). "At the ASCO 2020, data of C-144-01, a phase 2 trial including 66 patients with unresectable metastatic melanoma who have progressed on ICIs and BRAF/MEK inhibitors, were shown." (PMID 33804800, 2021). "Combined BRAF/MEK blockade results in rapid and robust disease control rates and remarkable ORR in BRAFV6oo-mutated metastatic melanoma." (PMID 33804800, 2021). "Currently, targeted therapies for metastatic melanoma mainly include BRAF and MEK inhibitors, such as Vemurafenib (the first FDA-approved BRAF inhibitor), dabrafenib, encorafenib, trametinib (the first FDA-approved MEK inhibitor), cobimetinib, and binimetinib." (PMID 33841154, 2021). "The introduction in clinical practice of new drug compounds both targeted therapies anti-BRAF and checkpoint inhibitors have largely improved our potential to manage advanced metastatic melanoma patients." (PMID 34447613, 2021). "In patients with BRAF V600 altered metastatic melanoma, are the incremental costs of triplet therapy of atezolizumab, vemurafenib plus cobimetinib vs vemurafenib plus cobimetinib alone cost-effective for the survival gains?" (PMID 34762112, 2021). "Acquired resistance to dabrafenib and trametinib occurs in most patients with BRAF-mutant metastatic melanoma and the majority of these patients fail the targeted therapy regimen." (PMID 34831014, 2021). "As targeted therapy using BRAF/MEK inhibitors has greatly improved the prognosis of patients with metastatic melanoma, the efficacy of these inhibitors has also been explored in patients with BM." (PMID 33816300, 2021). "As immunotherapies, BRAF and MEK inhibitors represented a turning point for the treatment of BRAF mutant metastatic melanomas with very high response rates and a significant benefit in terms of PFS and OS." (PMID 34447614, 2021). "In the IMspire150 trial, triplet treatment with atezolizumab and vemurafenib plus cobimetinib significantly improved progression-free survival (PFS) compared with vemurafenib plus cobimetinib alone for treatment of BRAF V600 variation metastatic melanoma." (PMID 34762112, 2021). "Disease progression for BRAF-mutant metastatic melanoma patients treated with a combination of dabrafenib and trametinib occurs within 9–10 months due to the development of resistance." (PMID 34831014, 2021). "In conclusion, our results indicate that the development of an early exanthema upon BRAF/MEK inhibition with COBIVEM is a surrogate marker of a favorable therapy outcome in metastatic melanoma patients." (PMID 34109122, 2021). "Given the results obtained in metastatic melanoma, several studies have reported the efficacy of anti-BRAF therapies in NSCLC treatment." (PMID 33474634, 2021). "mCRC treatment can be considered in terms of BRAF inhibition following the notably successful outcome of BRAF inhibition in BRAF mutant metastatic melanoma." (PMID 34946546, 2021). "In this study, patients with previously treated unresectable or metastatic melanoma, both mutant and wild type BRAF, are randomized to receive Spartalizumab combined with a second agent between Ribociclib, Capmatinib, Canakinumab, and LAG525." (PMID 34071228, 2021). "The COMBI-d and COMBI-v studies established the superior efficacy of dabrafenib + trametinib (dab + tram) versus BRAF inhibitor monotherapy in patients with BRAF V600–mutant metastatic melanoma." (PMID 34070224, 2021). "BRAF inhibitors (BRAFi) and MEK inhibitors (MEKi) provide rapid disease control in patients with BRAF-mutant metastatic melanoma." (PMID 33935743, 2021). "Our pre-clinical studies on patients’ HCL cells showed a promising anti-leukemic activity also for dabrafenib, another oral reversible ATP-competitive BRAF inhibitor approved in BRAF-V600E + metastatic melanoma." (PMID 33731847, 2021).
metastatic melanoma (continued). "Particularly in newly diagnosed, symptomatic, LDH-high metastatic melanoma, prompt treatment initiation with BRAF/MEK inhibition allows for a rapid tumor and clinical response in patients harboring mBRAF." (PMID 34359813, 2021). "ZEB1 antisense RNA 1 (ZEB1-AS) is a recent lncRNA whose expression levels have been associate not only to BRAF mutation, but also to RAS mutations in metastatic melanoma samples according to TCGA data." (PMID 33503876, 2021). "In summary, our study demonstrates that neither CT-based radiomics features, nor CT-derived LIDC features scored by a radiologist can discriminate between BRAF mutant and BRAF wild type lung metastases in patients with metastatic melanoma." (PMID 33915880, 2021). "Dabrafenib an FDA-approved inhibitor of mutant BRAF(V600) metastatic melanoma, but it can also target LIMK1 with nanomolar potency." (PMID 33883692, 2021). "As to metastatic melanoma, most studies have assessed the role of miRNAs as predictors of response to targeted therapies in BRAF-mutant patients." (PMID 33816298, 2021). "The pharmacological inhibition of the mitogen-activated protein kinases (MAPK) pathway by targeting the mutant v-Raf murine sarcoma viral oncogene homolog B1 (BRAF) is a milestone in the management of metastatic melanoma." (PMID 34447613, 2021). "Grover’s disease was observed in 42.9% of metastatic melanoma patients treated with a single BRAF inhibitor." (PMID 33216198, 2021). "PD-1 checkpoint blockade and BRAF- inhibition have shown OS benefits in metastatic melanoma, and thus, subsequent treatment has influenced patient OS in this trial." (PMID 34046035, 2021). "Targeted therapy with MAPKi regimens has dramatically changed the landscape of treatment of BRAF-mutant metastatic melanoma." (PMID 33868987, 2021). "In this retrospective analysis, we have analyzed and quantified the clinical activity and side-effects of CKI + TT in metastatic patients with BRAF mutant metastatic melanoma who progressed on their initial immunotherapy." (PMID 34743688, 2021). "Nearly half of patients with metastatic melanomas harbor a valine to glutamine substitution in codon 600 of the serine/threonine kinase BRAF." (PMID 33810240, 2021). "Fifty-six patients with wild-type BRAF metastatic melanoma were included with a median age of 68 years old (range: 40–84)." (PMID 34552135, 2021). "The COMBI-d and COMBI-v studies established the superior efficacy of the BRAF inhibitor dabrafenib (dab) in combination with the MEK inhibitor trametinib (tram) versus BRAF inhibitor monotherapy in patients with BRAF V600–mutant metastatic melanoma." (PMID 34070224, 2021). "It is noteworthy for the interpretation that, in 2010, the treatment of metastatic melanoma was improved by BRAF inhibitors, and in the following years by immunotherapy." (PMID 34711205, 2021). "Close intracranial monitoring and imaging follow-up should be conducted in metastatic melanoma patients on immunotherapy or a BRAF/MEK combination, even if they are asymptomatic." (PMID 33824801, 2021). "The approval was specified for the treatment of patients with unresectable or metastatic melanoma and disease progression after receiving ipilimumab and, in patients with BRAFV600 mutation, a BRAF inhibitor." (PMID 33677681, 2021). "Although combination BRAF and MEK inhibitors are highly effective for the 40–50% of cutaneous metastatic melanomas harboring BRAFV600 mutations, targeted agents have been ineffective for BRAFV600wild-type (wt) metastatic melanomas." (PMID 33826614, 2021). "The advent of BRAF inhibitor therapies has revolutionized the field of metastatic melanoma and papillary craniopharyngiomas." (PMID 33799709, 2021). "In a previous retrospective study, the disease course of 12 patients with metastatic melanoma who stopped BRAF inhibitor therapy after achieving a CR was analyzed." (PMID 33804800, 2021).
metastatic melanoma (continued). "Locally advanced unresectable and metastatic melanoma patients were given the option of systemic therapy with immune check point inhibitors or targeted therapy (in BRAF positive patients)." (PMID 34568037, 2021). "Since patients with metastatic melanoma can experience rapidly progressive disease with life-threatening symptoms and an urgent medical need for systemic therapy, faster and less invasive diagnostics to determine the BRAF mutation status may significantly improve patient management." (PMID 33915880, 2021). "The dabrafenib plus trametinib (dab + tram) combination has demonstrated durable long-term efficacy in patients with BRAF V600–mutant metastatic melanoma." (PMID 34070224, 2021). "Immune checkpoint inhibitors (ICI) and BRAF + MEK inhibitors combinations have dramatically changed the management of metastatic melanoma patients and improved outcomes." (PMID 34503304, 2021). "The present study was aimed to investigate the frequency and severity of an early exanthema upon BRAF and MEK inhibition with vemurafenib alone or combined with cobimetinib and its association with therapy outcome in patients with metastatic melanoma." (PMID 34109122, 2021). "Relevant clinical trials demonstrating efficacy of immune checkpoint inhibitors and BRAF kinase inhibitors and MEK kinase inhibitors (BRAF/MEK inhibitors) in unresectable/metastatic melanoma." (PMID 33804800, 2021). "Overall, results from the pooled analysis of both clinical trials suggest that patients with BRAF V600–mutant metastatic melanoma having a low initial tumor and disease burden are more likely to achieve long-term benefit from dab + tram therapy." (PMID 34070224, 2021). "We have already reported such a strategy in the treatment of metastatic melanoma with BRAF V600E/K inhibitors (BRAFi)." (PMID 33451095, 2021). "Future directions in the treatment of metastatic melanoma include immunotherapy with anti-PD1 antibodies or targeted therapy with BRAF and MEK inhibitors." (PMID 32671117, 2020). "The first drug used as BRAF inhibitor in patients with BRAF V600E advanced or metastatic melanoma was sorafenib (BAY 43-9006), which showed promising results in murine models but failed the human experimentation." (PMID 32760738, 2020). "BRAF and MEK inhibitors (BRAFi and MEKi) are the standard of care for the treatment of metastatic melanoma in patients with BRAFV600E mutations, greatly improving progression-free survival." (PMID 32708687, 2020). "The triple therapy combination of dabrafenib (BRAF inhibitor), trametinib (MEK inhibitor), and pembrolizumab (anti PD-1 antibody) were administered to patients with advanced BRAFV600-mutated metastatic melanoma." (PMID 32213878, 2020). "In our previous study, we demonstrated that in BRAF-mutant metastatic melanoma patients treated with a BRAF inhibitor, a higher expression of Y RNA-1 was associated with worse prognosis." (PMID 32947877, 2020). "Similar to CII resistance, different mechanisms have been associated with BRAF and MEK inhibitors resistance in metastatic melanoma." (PMID 33202891, 2020). "The development and use of the BRAF targeted inhibitors, Vemurafenib and dabrafenib, has improved the treatment arena for patients with metastatic melanoma." (PMID 32092958, 2020). "Although selective BRAF inhibitors and novel immunotherapies have improved short-term treatment responses in metastatic melanoma patients, acquired resistance to these therapeutics still represent a major challenge in clinical practice." (PMID 33184347, 2020). "We successfully developed BRAF-drug resistant cell lines from paired primary/metastatic melanoma cell lines in both 2D and 3D in vitro cultures." (PMID 32613561, 2020). "Approval of immune checkpoint-inhibitors (ICIs) and BRAF-inhibitors has revolutionized the treatment of metastatic melanoma." (PMID 32932758, 2020). "BRAF inhibitors can delay the progression of metastatic melanoma, but resistance usually emerges, leading to relapse." (PMID 32531927, 2020).